HSP90AB2P (heat shock protein 90 alpha family class B member 2, pseudogene)
Description:
Putative molecular chaperone that may promote the maturation, structural maintenance and proper regulation of specific target proteins.
Synonyms: HSP90BB
Gene: Processed pseudogene on chromosome 4 (13,336,482 to 13,338,657, forward strand). Ensembl gene ENSG00000205940.
Subcellular location: Cytoplasm
Diseases named in the same sentence as HSP90AB2P in open-access papers:
HSP90AB2P is named in the same sentence as 3 diseases in open-access papers, as found by Europe PMC text mining. Sharing a sentence is not in itself a finding about the gene and the disease.
HSP90AB2P shares sentences with these, for which no sentence is quoted: breast carcinoma (1 paper); Salmonella Infections (1); tumor (1).